GOLGA8CP (golgin A8 family member C, pseudogene)
Synonyms: GOLGA8C
Gene: Transcribed unprocessed pseudogene on chromosome 15 (20,562,375 to 20,575,696, forward strand). Ensembl gene ENSG00000181984.
Diseases named in the same sentence as GOLGA8CP in open-access papers:
GOLGA8CP is named in the same sentence as 2 diseases in open-access papers, as found by Europe PMC text mining. Sharing a sentence is not in itself a finding about the gene and the disease.
GOLGA8CP shares sentences with these, for which no sentence is quoted: B cell CLL (1 paper); lymphoma (1).